NLRP3 (NLR family pyrin domain containing 3)
Diseases named in the same sentence as NLRP3 in open-access papers (continued):
Sharing a sentence is not in itself a finding about the gene and the disease.
asthma (continued). "Interestingly, some compounds already in use for the treatment of asthma or to attenuate airway inflammation have been found to be effective at least partially because they are able to inhibit the NLRP3 inflammasome." (PMID 36189256, 2022). "Inflammasomes are a family of multiprotein signaling complexes and nucleotide-binding oligomerization domain (NOD)-like receptors (NLR), of which NLRP3 (NOD-like receptor family pyrin domain-containing 3) inflammasomes are particularly important in the pathogenesis of asthma." (PMID 35711428, 2022). "In the context of asthma, although many NLR functions and mechanisms are still unknown, it is now clear that at least some of them, namely NOD1, NOD2, and NLRP3, play crucial roles in the development, regulation, and exacerbation of asthma." (PMID 36189256, 2022). "Additionally, it was confirmed in the Nlrp3Y30E/Y30E mutant mouse model that active NLRP3 inflammasome promoted inflammation and pathological tissue damage in asthma in an inflammasome-dependent manner." (PMID 36203607, 2022). "Altogether, although still controversial, these data suggest that NLRP3 may play a role in both T2 low neutrophilic and T2 high eosinophilic severe asthma." (PMID 36189256, 2022). "In addition, we also summarized the latest research results that NLRP3 inflammasomes are involved in the chronic inflammatory process of asthma and COPD." (PMID 36444628, 2022). "The NLRP3 inflammasome plays a key role in the pathogenesis of asthma." (PMID 35711428, 2022). "In addition to asthma and COPD, the NLRP3 inflammasome also involved in the pathogenic process of various diseases." (PMID 36444628, 2022). "The purpose of this review is to collate recent advances in the activation and regulation of the NLRP3 inflammasome and the evidence for the relationship between the NLRP3 inflammasome and lung diseases, especially literature reports related to asthma and COPD." (PMID 36444628, 2022). "However, excess or persistent activation of NLRP3 inflammasomes by allergens or irritants has been shown to induce persistent inflammation and tissue damage in the airway of patients with asthma." (PMID 35626330, 2022). "NLRP3 expression has been described in different human cell subsets that could potentially play relevant roles in asthma pathogenesis." (PMID 36189256, 2022). "This study was the first to explore the correlation between NLRP3 rs10925023 and asthma." (PMID 36595748, 2022). "Autophagy inhibits NLRP3-induced monocyte activation in the asthma model." (PMID 35619697, 2022). "In ob/ob and HFD-induced obese mice suffering from airway diseases, IL-17A, NLRP3, and ILC3s are essential parts of inflammation, whereas type 2 responses may be unnecessary for an obese asthma phenotype." (PMID 36051916, 2022). "The levels of NLRP3 mRNA in steroid resistant asthmatics correlate with the numbers of neutrophils, and the severity of asthma, while levels of IL-1 β correlate with IL-8, a neutrophil attracting chemokine, suggesting a role of NLRP3 in the neutrophil asthma phenotype." (PMID 36189256, 2022). "In addition, pyroptosis of bronchial epithelial contributes to hyperresponsiveness and airway inflammation in toluene diisocyanate-induced asthma through activation of NLRP3 inflammasome and GSDND cleavage." (PMID 36213326, 2022). "NLRP3 expression has also been shown to be increased in obese patients with asthma." (PMID 35626330, 2022). "As resident myeloid cells in the lung, alveolar macrophages are an obvious candidate where NLRP3 could play a role in the development of asthma." (PMID 36189256, 2022). "More and more studies have found that the NLRP3 inflammasome may be involved in the chronic inflammatory process of asthma." (PMID 36444628, 2022). "Also, sevoflurane, a commonly used volatile anaesthetic, has a comparable to MCC950 favourable effect on NLRP3 inflammasome inhibition and decreases asthma symptoms." (PMID 36203607, 2022).
asthma (continued). "Furthermore, inflammasomes (such as NLRP3) and caspases (such as caspase‐1/11) have been reported to participate in asthma." (PMID 34590363, 2021). "While NLRP3 inflammasome has been considered to be critical in the clearance of pathogens in the airways, study suggests that environmental allergen and irritant-induced persistent NLRP3 inflammasome activation plays a strong role in the exacerbation of asthma features." (PMID 34868022, 2021). "We used an HDM-induced asthma model in Nlrp3-/- mice and wild-type mice." (PMID 34413860, 2021). "Particulate matters, ozone and apoliopoprotein E can aggravate asthma via NLRP3 inflammasome." (PMID 33546184, 2021). "In addition, it has been demonstrated that NLRP3 in TH2 cells promotes the type II immune response in asthma." (PMID 34413860, 2021). "The results demonstrated that NLRP3 promoted inflammation in asthma by forming inflammasomes." (PMID 34413860, 2021). "By inducing an asthma model in Nlrp3Y30E/Y30E-mutant mice, which completely abrogates inflammasome activation without altering the expression of NLRP3, we demonstrated that the inflammasome activity of NLRP3 was critical for the development and progression of asthma." (PMID 34413860, 2021). "To further investigate whether the therapeutic effects of RRx-001 on asthma are dependent on NLRP3, we treated HDM-challenged Nlrp3-/- mice and wild-type mice with RRx-001 and vehicle." (PMID 34413860, 2021). "Activation of NLRP3 has been observed in both asthma and fibrosis, and its inhibition may represent a new target in the management of chronic lung injury." (PMID 34445540, 2021). "Furthermore, we identified a new player, the NLRP3 inflammasome-mediated IL-1β, which can drive airway mucus overproduction in asthma (See Graphic abstract)." (PMID 34868022, 2021). "Although NLRP3 has been identified to promote airway inflammation in allergic asthma, whether the inflammasome activity of NLRP3 alters the progression of asthma is unclear." (PMID 34413860, 2021). "To explore whether activation of the NLRP3 inflammasome is involved in the progression of asthma, we applied the HDM model in Nlrp3Y30E/Y30E mutant mice." (PMID 34413860, 2021). "Activation of caspase-1 even dampens IL-33-dependent allergic asthmatic inflammation.The involvement of NLRP3 is also reported in neutrophilic asthma, another type of asthma that is often associated with non-allergic exposure." (PMID 33546184, 2021). "Here we will focus on the role of miR-223 and NLRP3 in the context of asthma and COPD." (PMID 32509795, 2020). "The use of the NLRP3 inhibitor MCC950, the caspase-1 inhibitor Ac-YVAD-CHO and IL-1β neutralizing antibodies effectively reduce the asthma-induced inflammatory response, indicating that activation of the NLRP3 inflammasome and induction of IL-1β are important components in inflammation in the body." (PMID 32293543, 2020). "Accumulating evidence proposes that NLRP3 activation is critically involved in asthma pathogenesis." (PMID 31590215, 2019). "Taken together, these studies indicate that pharmacological inhibition of NLRP3 might be beneficial for the treatment of inflammatory diseases, including asthma." (PMID 30373775, 2019). "Here, we provide an overview of the pathophysiology of SA, present molecular mechanisms underlying aberrant inflammatory responses in the airways, summarize recent studies pertinent to the biology and functions of NLRP3, and discuss the role of NLRP3 in the pathogenesis of asthma." (PMID 31590215, 2019). "Notably, administration of NLRP3 inhibitors in asthma models restrains AHR and pulmonary inflammation." (PMID 31590215, 2019). "A series of recent studies suggest that NLRP3 activation is involved in human asthma pathogenesis." (PMID 31590215, 2019).
asthma (continued). "In the next section, we describe current knowledge on the role of NLRP3 activation in the initiation and propagation of allergic airway inflammation and human asthma, and discuss the implications of excessive NLRP3 responses in the pathogenesis of allergic diseases." (PMID 31590215, 2019). "In fact, although NLRP3 facilitates the clearance of pathogens in the airways, persistent NLRP3 activation by inhaled irritants and/or innocuous environmental allergens can lead to overt pulmonary inflammation and exacerbation of asthma manifestations." (PMID 31590215, 2019). "NP inhalation could increase chronic pulmonary disorder susceptibility; however, the definitive function of NLRP3 in chronic obstructive pulmonary disease (COPD) and asthma is unclear." (PMID 30447690, 2018). "In asthma models, the role of the NLRP3 inflammasome remains controversial." (PMID 30363922, 2018). "Recently, it has been reported that NLRP3 acts as a key transcription factor in Th2 differentiation in asthma models, suggesting that sevoflurane may inhibit Th2 responses via NLRP3 in our model." (PMID 30363922, 2018). "However, other studies have shown that NLRP3 expression drives the polarization of M2 macrophages in asthma through upregulation of IL-447 and Il4 promoter binding and transactivation in conjunction with the transcription factor IRF448." (PMID 30518854, 2018). "However, a study demonstrated that activation of the TLR2/NLRP3/IL‐18 axis can protect against asthma 3, complicating the role of IL‐18 in asthma." (PMID 28922563, 2018). "Using the String database to visualize the matching gene of the NOD-like receptor pathway, we found that the NLRP3 inflammasome might play an important role in the process that YPFS regulating the asthma." (PMID 29311942, 2017). "In addition, we evaluated the relationship of serum vitamin D levels and obese asthma outcomes, and the activity of NLRP3 inflammasome in the animals." (PMID 29160418, 2017). "Furthermore, obese asthma mice exhibited significantly lower vitamin D levels in serum and significantly higher NLRP3 and IL-1β mRNA expression levels in lung tissue." (PMID 29160418, 2017). "Lower vitamin D3 levels may influence proinflammatory cytokines and NLRP3 inflammasome activity in obese asthma." (PMID 29160418, 2017). "There’s studies proved that NLRP3 mediated IL-1β could lead to a vicious cycle between previous and future exacerbations in asthma." (PMID 29311942, 2017). "We also evaluated NLRP3 inflammasome activity in the pathogenesis of obese asthma." (PMID 29160418, 2017). "Our data in this research demonstrated that YPFS could attenuate inflammatory response in asthma through suppressing the NLRP3 inflammasome." (PMID 29311942, 2017). "In conclusion, these results demonstrated that YPFS could inhibit NLRP3 inflammasome components to attenuate the inflammatory response in asthma." (PMID 29311942, 2017). "In addition, NOD-like receptor family pyrin domain-containing 3 (NLRP3) inflammasome was treated as target protein in the process of YPFS regulating asthma." (PMID 29311942, 2017). "The references cited in this review demonstrate that the development of lung cancers, MMs, asbestosis and silicosis, asthma, and COPD are associated with acute or chronic inflammation and activation of the NLRP3 inflammasome by several different pathogenic particles and fibres." (PMID 27650313, 2016). "It has been documented that NLRP3 inflammasome which is responsible for IL-1β maturation may play crucial roles in OVA-induced asthma." (PMID 27793052, 2016). "Recent advances in the study of leucine-rich repeat protein 3 (NLRP3) inflammasome may also provide a potential link between asthma and CKD." (PMID 24885269, 2014).
asthma (continued). "Notably, cytoplasmic viral components can also activate the non-canonical inflammasome pathway, engaging caspase-4/5 in humans (caspase-11 in mice), which cleaves GSDMD independently of NLRP3, triggering further epithelial barrier disruption and exacerbating viral-induced asthma flare-ups." (PMID 41394843, 2025). "Crucially, we contextualize pyroptosis within distinct asthma endotypes, proposing that allergen-driven, NLRP3-dominated pathways may underpin Th2-high/eosinophilic inflammation, while pollutant/viral-triggered, non-canonical/AIM2 pathways may favor Th2-low/neutrophilic phenotypes." (PMID 41394843, 2025). "Furthermore, exaggerated activation of the NLRP3 inflammasome and production of IL-1β may be correlated with asthma disease severity." (PMID 40343297, 2025). "Specifically, NLRP3 levels in induced sputum are significantly elevated in children with asthma, with further elevation observed in those with moderate-to-severe disease, suggesting that induced sputum NLRP3 may serve as a potential biomarker for assessing asthma severity." (PMID 40832584, 2025). "Thus, the inhibition of NLRP3- or GSDMB-mediated pyroptosis in AECs may reduce asthma severity and exacerbations." (PMID 39611173, 2024). "IL-1β produced after the activation of NLRP3 inflammasome positively regulates the differentiation of Th17 cells, which promotes the secretion of IL-6 and IL-8 and induces neutrophil recruitment, which may be an important factor in the acute attack of asthma." (PMID 38117410, 2024). "However, whether MUC1 regulates NLRP3 inflammasome-mediated pyroptosis through the TLR4/MyD88/NF-κB pathway in asthma remains unknown." (PMID 37880668, 2023). "We hypothesized that the ability for NLRP3 inflammasome priming and/or activation and IL-1β release are increased, and can be therapeutically inhibited, in immune cells from patients with severe asthma." (PMID 38044426, 2023). "However, the exact mechanism of NLRP3 inflammasome activation and apoptosis in asthma remains unknown." (PMID 38274803, 2023). "Thus, DEK may regulate airway inflammation in asthma by managing the mtROS, NLRP3 inflammasome, and apoptosis of airway epithelial cells." (PMID 38274803, 2023). "Targeting the upstream of NLRP3 inflammasome-mediated pyroptosis and simultaneously inhibiting multiple targets may have a better therapeutic effect on neutrophil airway inflammation in asthma." (PMID 37880668, 2023). "There may be interactions between NLRP3 and MAVS polymorphisms in the risk of asthma." (PMID 36595748, 2022). "However, while most of the asthma model hallmarks such as AHR did not present significant changes between the NLRP3 deficient mice and the WT, the levels of IL13 and IL33 were slightly but significantly attenuated." (PMID 36189256, 2022). "Indeed, it has been reported that NLRP3 expression is significantly increased in severe asthma patients where it could be participating in predominantly Th2 responses." (PMID 36189256, 2022). "We found several additional pathways of importance to asthma enriched in the baseline sample and stimulated transcriptomic differences in cluster 1 compared with cluster 2 including TNFα receptor binding, apoptosis, the NLRP3 inflammasome, and estrogen receptor signaling." (PMID 36385161, 2022). "However, the implication of NLRP3 in asthma has been a matter of controversy." (PMID 36189256, 2022). "However, the detailed role of NLRP3 inflammasome in asthma and COPD remains controversial." (PMID 36444628, 2022). "Similarly, compared to the control mice, mice with OVA-induced asthma showed a significantly higher expression of NLRP3, Caspase-1, IL-1β in the lung tissues, and the expression of these key proteins was significantly decreased in asthmatic mice treated with QF." (PMID 36081945, 2022). "Interactions between NLRP3 and MAVS polymorphisms may affect the risk of asthma." (PMID 36595748, 2022). "Thus, the cell source of NLRP3 that affects the progression of asthma needs to be investigated." (PMID 34413860, 2021).
asthma (continued). "Moreover, previous clinical and experimental studies have demonstrated that the expression of NLRP3 inflammasome is up-regulated in asthma patients and in the OVA-induced asthma model, illustrating the vital role of NLRP3 inflammasome in the pathology of asthma." (PMID 33645621, 2021). "In addition, previous evidence indicates that the activation of NLRP3 inflammasome may lead to increased release of IL-1b and that this increase may be a key factor inducing inflammation and resulting in asthma and may serve as a marker for asthma." (PMID 33645621, 2021). "Our results showed that the mRNA and protein levels of NLRP3, ASC and Caspase-1 in the lungs of OVA-induced asthmatic mice were notably down-regulated after ACG treatment, suggesting that ACG might inhibit the inflammatory response in OVA-induced asthma by suppressing the NLRP3 inflammasome." (PMID 33645621, 2021). "Therefore, we selected RRx-001 to target NLRP3 in asthma, and it showed strong therapeutic effects." (PMID 34413860, 2021). "Thus, we determined that the NLRP3 inflammasome promoted the inflammatory response in asthma and could be a target for asthma therapy." (PMID 34413860, 2021). "However, the mechanism by which NLRP3 affects asthma requires further investigation." (PMID 34413860, 2021). "Therefore, we hypothesized that the maturation of IL-1β in the lungs was dependent on the activation of the NLRP3 inflammasome in HDM-induced asthma." (PMID 34413860, 2021). "Thus, we explored the effect of this safe and effective NLRP3 inhibitor on asthma." (PMID 34413860, 2021). "The activation of the NLRP3 inflammasome has also been suggested to be involved in acute lung inflammation after viral/bacterial infection and during the progression of several chronic pulmonary diseases, including idiopathic pulmonary fibrosis, chronic obstructive pulmonary disease, and asthma." (PMID 30622955, 2018). "First, we hypothesized that NLRP3 may direct inflammasome activation in asthma." (PMID 30363922, 2018). "Further research revealed that NLRP3 inflammasome-mediated IL-1β might be one of the key factors which could induce inflammation and result in asthma, and increasing IL-1β could also be seen as a marker of asthma." (PMID 29311942, 2017). "Moreover, previous clinical and experimental studies demonstrated that the expression of NLRP3 inflammasome was up-regulated in patients with asthma and OVA-induced asthma model, which indicated NLRP3 inflammasome played an important role in the pathology of asthma." (PMID 29311942, 2017). "Our findings demonstrate that KIF1B plays a crucial role in promoting asthmatic inflammation through NLRP3‐mediated pyroptosis, identifying KIF1B as a novel therapeutic target for asthma intervention." (PMID 41384344, 2025). "Furthermore, they imply that NLRP3 plays a pivotal role in asthma development, with its effects being partially reflective of the various underlying immune mechanisms of this heterogeneous disease, and that targeting NLRP3 could lead to different therapeutic outcomes depending on the asthma subtype." (PMID 41394833, 2025). "Previous research has shown that the expression of the NLRP3 inflammasome and its downstream product, IL-1β, is increased in the BALF of a mouse model of asthma." (PMID 40343297, 2025). "Protopine, which is an anti-inflammatory isoquinoline alkaloid obtained from plants, ameliorates OVA-induced asthma by downregulating the TLR4/MyD88/NF-κB signaling, and reducing NLRP3-mediated pyroptosis." (PMID 39611173, 2024). "It has previously been reported that NLRP3 promotes M2 polarization in asthma models and is able to induce PDL1 in lymphoma, and supporting this, our data showed that T. crassiceps dramatically relies on NLRP3 to recruit macrophages and reprogram them." (PMID 38842647, 2024). "Recent findings have reported that Chlamydia and Haemophilus infections increased expression levels of NLRP3, caspase-1 and IL-1β in OVA-induced severe asthma murine model." (PMID 38811424, 2024).